INS (insulin)
Diseases named in the same sentence as INS in open-access papers (continued):
Sharing a sentence is not in itself a finding about the gene and the disease.
breast cancer (continued). "A positive association between circulating concentrations of insulin or C-peptide and breast cancer risk has been observed in several, but not in all epidemiologic studies." (PMID 20184722, 2010). "Thus, animals in the LPHC group were likely exposed to higher, repeated elevations in serum insulin following each discrete meal during the period leading to the emergence of palpable mammary tumors." (PMID 20148110, 2010). "Goodwin and colleagues have administered Metformin, an oral anti-diabetic drug, to lower insulin levels in women with early breast cancer, and are trying to evaluate the effect of the novel approach on breast cancer outcomes in the later stage of the clinical trial." (PMID 24281091, 2010). "Furthermore, insulin is highly regulated by endogenous sex hormones, particularly by estrogens - the hormone involved in the promotion and growth of breast cancer." (PMID 24281091, 2010). "Several studies have supported an association of elevated insulin production and/or insulin concentrations and decreasing levels of IGFBP-3, with an increased risk of developing several malignancies including colorectal and breast cancer." (PMID 16570048, 2006). "Insulin and the insulin-like growth factors (IGFs) may be important regulators of breast cancer growth." (PMID 8286193, 1994). "However, evidence linking insulin use with breast cancer remains conflicting." (PMID 41334715, 2025). "In light of the previously reported ability of insulin to promote primary tumour growth and metastasis and the higher breast cancer mortality in subjects with high insulin level, we evaluated if this condition could enhance the migration of the studied BC cell lines." (PMID 40806650, 2025). "A multicentric case–control study performed across 92 institutions in the UK, US, and Canada, including 775 women with DM diagnosed with breast cancer, found no significant risk difference between human insulin users and insulin glargine users (HR 1.29, 95% CI 0.78–2.13)." (PMID 39434861, 2024). "Furthermore, insulin and IGFs may influence breast cancer progression by interacting with other growth factors and receptors involved in cell growth and survival." (PMID 39767777, 2024). "Consequently, we propose that the elevated risk of breast cancer associated with ASB may be attributed to dysregulated glucose metabolism and insulin dysfunction." (PMID 38524848, 2024). "However, in premenopausal women, high circulating insulin levels may protect against breast cancer, the same as obesity." (PMID 38734800, 2024). "Overweight or obese women with normal insulin levels are not at higher risk of breast cancer." (PMID 37096432, 2023). "Thus, the effects of exercise on breast cancer outcomes may be mediated by insulin resistance and inflammatory markers." (PMID 36864418, 2023). "Furthermore, the Reach for Health study demonstrated that improved glycaemic control achieved via metformin therapy and weight loss had a positive impact on the plasma insulin, SHBG and oestrogen concentrations in postmenopausal breast cancer survivors who were either overweight or obese." (PMID 37047163, 2023). "Fifth, we were unable to examine the effect of four measures of insulin secretion (AUCins/AUCgluc, AUCins, Ins30, and Ins30 [BMI adj.]), influenced by E354Q, on breast cancer risk due to the lack of genome-wide significant variants available to serve as instruments for these measures." (PMID 37250804, 2023). "These measures confer opposing effects on breast cancer risk, suggesting perturbed glycemic and/or other adverse effects of impaired GIPR signaling through this mechanism offset possible beneficial effects on insulin secretion and circulating testosterone levels." (PMID 37250804, 2023).
breast cancer (continued). "Patients who used only metformin (64.3%) or metformin with insulin (14.4%) were less likely to have breast cancer (i.e., metformin and metformin with insulin decrease the risk of breast cancer); no studies in the literature mention both medications (i.e., insulin and metformin)." (PMID 36766896, 2023). "Five anticancer drugs had higher and lower sensitivity to high BCCuS group, such as Phenformin, which can improve insulin sensitivity of breast cancer tissue, consuming nucleotide triphosphate and may hinder nucleotide synthesis, thus playing a role in inhibiting cancer." (PMID 36699089, 2022). "Furthermore, support for a potential metformin treatment mediated by reducing serum levels of insulin and other metabolic markers, such as serum levels of glucose, leptin, and high-sensitivity C-reactive protein (hsCRP) in a group of breast cancer patients was provided." (PMID 35267644, 2022). "However, none of the glycaemic traits had a substantial effect on breast cancer risk (fasting insulin OR: 1.00 [0.58:1.72], fasting glucose OR: 1.03 [0.85: 1.25], Hba1c OR: 1.02 [0.74: 1.4], HOMA-B OR: 1.06 [0.78: 1.45]." (PMID 35396499, 2022). "Comparisons of gene expression data from the TCGA breast cancer patients with the genotype homozygous for the minor alleles of the SNPs in WSCD2 and MT-ND4 versus the other genotypes revealed core transcriptional regulator interactions and an association with insulin." (PMID 35082309, 2022). "Mechanistically, testosterone and insulin mediated 21% and 35%, respectively of the total, genetically determined association of BMI with endometrial cancer risk whilst HDL cholesterol and IGF-1 mediated 40% and 22%, respectively of the association between BMI and breast cancer risk." (PMID 36558416, 2022). "Similarly, the Women’s Health Initiative Observational Study (WHI-OS) of 93,676 postmenopausal women, insulin levels were associated with a > 2.4-fold increase in breast cancer risk in women not on hormone-replacement therapy." (PMID 35984550, 2022). "Meanwhile, it would beinteresting to investigate, in a new study, the expressionof other molecules involved in this signaling pathway.Our observations could help clarifying one of the possiblemechanisms of insulin-induced drug resistance in MCF-7 as a well-known breast cancer cell line." (PMID 34308576, 2021). "Several studies have linked elevated levels of serum C-peptide (a stable marker of insulin secretion that is co-secreted with insulin) with enhanced risk of post-menopausal endometrial cancer, colorectal cancer and breast cancer, but not pre-menopausal, ovarian, breast and prostate cancers." (PMID 34535145, 2021). "Leptin levels, both in circulating plasma or expression in breast cancer tissue, are reported to have association with breast cancer progression Leptin and leptin receptor are overexpressed in breast cancer tissue probably due to hypoxia, IGF, estradiol, and insulin overexposure." (PMID 33482868, 2021). "When stratified by levels of insulin and the IGF axis biomarkers, participants with low insulin (HR: 1.42; 95% CI: 1.11–1.82), low C-peptide (HR: 1.41; 95% CI: 1.10–1.80), and low IGF1/IGFBP3 ratio (HR: 2.55; 95% CI: 1.18–5.49) exhibited increased risk of breast cancer recurrence." (PMID 34456877, 2021). "The tumor suppressor factor is of a similar value whether the malignancy is mesothelioma primary arising from inhaled asbestos, cervical cancer from exposure to human papillomavirus, melanomas from sun exposure, or post-menopausal breast cancer with elevated insulin levels." (PMID 34695806, 2021). "Thus, insulin promoted breast cancer cell proliferation, migration, and tumor formation in vitro." (PMID 33495474, 2021). "Several reports indicate that overweight with normal insulin sensitivity does not have increased risk for cardiovascular disease, which might also be the case for breast cancer." (PMID 34707572, 2021).
breast cancer (continued). "However, in a recent study, we demonstrated that the fasting-mediated enhancement of endocrine therapy activity in hormone receptor-positive breast cancer (HR+ breast cancer) also relies on the ability of fasting to blunt circulating insulin and leptin concentrations." (PMID 34439167, 2021). "First, previous studies did not assess whether the association between serum C-peptide levels and breast cancer is independent of serum insulin level but only as an indicator of insulin secretion." (PMID 33180852, 2020). "Previous studies describe insulin activated critical intracellular signaling pathways including phosphatidylinositol 3-kinase/AKT kinase (PI3K/Akt) pathway or RAF kinase/mitogen activated protein kinase (Ras-MAPK pathway) to promote breast cancer growth and invasion." (PMID 32631390, 2020). "This suggests that the association between metabolic features such as increased fasting insulin levels and breast cancer risk may be independent of higher adiposity." (PMID 32705315, 2020). "Moreover, this is the first study to investigate the association between serum C-peptide level and breast cancer independent of insulin level as a bioactive peptide." (PMID 33180852, 2020). "In addition, whether the cross talk between insulin and IGF signaling pathways may influence the associations between biomarkers of the IGF axis and the prognosis of breast cancer is unclear." (PMID 32974138, 2020). "Therefore, tumor size combined with insulin c-peptide status may predict an increased effect of adjuvant metformin or other insulin-lowering drugs in the treatment of breast cancer patients." (PMID 31703648, 2019). "Although the mechanism by which insulin B10 aspart increases the risk of breast cancer is not clear, many studies have proposed that this may be due to the high affinity of insulin B10 aspart for IGF-1R." (PMID 31555212, 2019). "Moreover, S1PR3 was important for insulin-mediated mitogenic action in breast cancer cells." (PMID 29385066, 2018). "However, among postmenopausal women without a history of breast cancer, exercise added to weight loss did not further improve fasting insulin or insulin resistance and is consistent with our findings." (PMID 29587682, 2018). "Insulin secretion.Axonal growth; endothelial sprouting.Antithrombin binding.Hypermethylation as marker in multiple cancers.Zebrafish development.Inflammatory stimuli in Monocytes.Promotes Angiogenesis.Marker for breast cancer.Novel inducer of Pancreatic cancer.Cardiac Rhythm." (PMID 30555321, 2018). "Furthermore, increase in MD in women taking insulin may reduce the sensitivity of the screening in this group of diabetic women, as breast cancer screening performance decreases with increasing breast density." (PMID 27832382, 2017). "However, the mechanism responsible for the regulatory effects of miR-29a on breast cancer growth and invasion and the relationship between these effects and insulin signaling remains unclear." (PMID 28427228, 2017). "Moreover, increased insulin levels are associated with greater estrogen production, which can have negative effects on breast cancer." (PMID 28178355, 2017). "However, it is not clear whether miR-29a is involved in the regulatory mechanisms by which insulin promotes breast cancer cell proliferation and invasion." (PMID 28427228, 2017). "Because of its ability to bind different substrates, insulin can activate different insulin signaling pathways (such as the phosphatidylinositol 3-kinase/AKT kinase (PI3K/Akt) pathway or RAF kinase/mitogen activated protein kinase (Ras-MAPK pathway)) to promote breast cancer growth and invasion." (PMID 28427228, 2017). "Therefore, insulin can promote breast cancer cell invasion and metastasis, which may be achieved by promoting endogenous miR-29a expression in breast cancer cells." (PMID 28427228, 2017).
breast cancer (continued). "Specifically, the breast cancer incidence rate in these women was two-fold greater among those in the highest two quartiles compared with those in the lowest quartile of CRP, even after controlling for estradiol, insulin, BMI and established breast cancer risk factors." (PMID 27338371, 2016). "While most insulin analogues, including glargine, were negative in these chronic bioassays, several epidemiological studies showed an increased breast cancer risk, which could not be observed by others." (PMID 25848982, 2015). "TCC practice in breast cancer survivors significantly enhanced functional capacity and health-related life quality, decreased fat mass with increased IL-6 and decreased IL-2 levels, and maintained insulin level compared to the breast cancer survivors only receiving psychosocial support." (PMID 25653009, 2015). "Although, there is evidence from in vitro data that insulin glargine has increased mitogenic potential, so far, epidemiological studies have not shown evidence for an association between insulin (analogue) treatment and breast cancer risk in female diabetic patients." (PMID 26242987, 2015). "In Model IV, human insulin users without use of ACEI/ARB or with a short-term use of ACEI/ARB for <2 years had a significantly lower risk of breast cancer, while those who had been treated with ACEI/ARB for a longer term (≥2 years) showed a neutral risk association." (PMID 26537234, 2015). "While we studied the effect of insulin analogues on MG tumor development, we cannot exclude that insulin analogues with high affinity for the IGF1R may also promote breast cancer progression, either locally or at distant sites, or modulate sensitivity to anticancer drugs." (PMID 25848982, 2015). "Whether insulin glargine or other insulin analogs may increase the risk of breast cancer is not evaluated in the present study, but this can be an important issue worthy of further investigation." (PMID 26537234, 2015). "Using individual odds ratios (ORs) adjusted at least for age, there was no higher risk of breast cancer when upper quartiles were compared with the lowest quartile (Q1) of fasting insulin levels (OR Q2 vs. Q1 0.96, 0.71 to 1.28; OR Q3 vs. Q1 1.22, 0.91 to 1.64; OR Q4 vs. Q1 0.98, 0.70 to 1.38)." (PMID 24911052, 2014). "Other studies focusing on cocoa positive health outcomes include: increase in insulin sensitivity and decrease in blood pressure, cocoa as gastro-protective cocoa and improved cognition, cocoa blocks UV-induced erthema and improves skin condition, and cocoa inhibits growth of breast cancer cells." (PMID 24077240, 2013). "Additionally, Notch activation could enhance the oncogenic potential of other molecules with an important role in obesity and breast cancer angiogenesis, i.e., insulin and IGF-1." (PMID 24202338, 2013). "Therefore, the aim of our study was to examine whether patients with DM using insulin glargine have a higher tumor stage of breast carcinoma in comparison to patients using other types of insulin." (PMID 24131755, 2013). "Alterations in the metabolism of endogenous hormones such as insulin, sex hormones and levels of insulin-like growth factor (IGF)- I, and IGF-binding proteins (IGFBPs), may form the causal pathways linking excess weight and breast cancer risk." (PMID 23397025, 2012). "Additionally, most breast cancer cell lines are insulin-independent for growth." (PMID 21437235, 2011). "Furthermore, interim analyses of ongoing studies involving neoadjuvant metformin treatment of newly diagnosed breast cancer patients have demonstrated that metformin is safe and well tolerated, and exhibits favorable effects on insulin metabolism and tumor cell proliferation and apoptosis." (PMID 21470407, 2011). "Insulin is believed to increase breast cancer risk through mitogenic, and not mutagenic mechanisms, and may therefore act at a late stage in cancer development." (PMID 21811252, 2011).
breast cancer (continued). "Because low HDL-C is related to increased levels of several cancer-promoting hormones (e.g., androgens, estrogens, insulin, and IGF-I), the observed association may reflect the relative importance and mutual dependence of different disease pathways in malignant breast tumours after menopause." (PMID 18665244, 2008). "Both insulin and IGF-1 can promote cell proliferation and inhibit apoptosis in breast cancer cells, even at physiologically relevant concentrations." (PMID 40764810, 2025). "Breast cancer cells release IGFBP5, IGF-I and insulin, and they regulate tumor progression in a paracrine and endocrine manner." (PMID 38896333, 2024). "In this review, we describe the influence of antidiabetic drugs from insulin and metformin to the current and emerging therapies, incretins and SGLT-2 inhibitors, on breast cancer prognosis." (PMID 38254789, 2024). "We demonstrate a novel function of IGFBP5 in the regulation of IGF-IR expression, migration and MMP-9 secretion induced by IGF-I and/or insulin, and in the spheroids formation in MCF-7 breast cancer cells." (PMID 38896333, 2024). "It delves into the impact of antihyperglycemic therapy, including insulin, metformin, and novel groups: incretins and SGLT-2 inhibitors, on the prognosis of breast cancer in diabetic patients." (PMID 38254789, 2024). "The cell experiments in our study also showed that MARCH1 mediated the TBK1-mTOR signaling pathway to both respond to insulin and EGF stimulation in breast cancer cells." (PMID 39061024, 2024). "However, other research indicates that although insulin analogs might promote tumor progression by upregulating mitogenic signaling pathways, there is no strong evidence that they, or human insulin, increase the risk of breast cancer." (PMID 39457586, 2024). "IGFBP5 regulates IGF-IR expression, migration and MMP-9 secretion induced by IGF-I and/or insulin, and the spheroids formation in MCF-7 breast cancer cells." (PMID 38896333, 2024). "To investigate the potential effects of insulin on ARG treatment, we first determined the expression of insulin receptor on six breast cancer cell lines, three lung cancer cell lines, and three ovarian cancer cell lines." (PMID 38374190, 2024). "This indicates that single indicators such as insulin or glucose may not be a good indicator for breast cancer in different populations, whereas the association between HOMA-IR and breast cancer suggests that it may be more beneficial to use multifactor indicators." (PMID 38904041, 2024). "Out of the three breast cancer cell lines, only MDA-MB-231 was able to recover following treatment with ARG, and recovery appeared unaffected by insulin." (PMID 38374190, 2024). "Under insulin treatment, increased breast density in T2DM patients diagnosed with breast cancer (TNBC) can also complicate cancer screening and diagnosis." (PMID 37510134, 2023). "However, whether women with high body fatness but normal insulin levels or those with normal body fatness and high levels of insulin are at elevated risk of breast cancer is not known." (PMID 37096432, 2023). "Insulin and insulin-like growth factor 1 (IGF1) are metabolic hormones, which are often upregulated to stimulate proliferation in breast cancer." (PMID 38136416, 2023). "Insulin/IGF1R signaling has significant implications for treatment of and survival following breast cancer." (PMID 37237509, 2023). "The fact that IR is not enriched in the CSC population, and that IGF-1 and IGF-2 are more effective regulators of CSC function than insulin, supports a dominant role for the IGF-1R in regulating breast cancer stemness." (PMID 36556357, 2022). "Aberrant reprogramming of energy metabolism was frequently detected in many types of carcinomas including breast cancer, and CHES1 has been reported to modulate glucose homeostasis and insulin sensitivity in zebrafish and mouse models." (PMID 36450706, 2022).